GPR142 (G protein-coupled receptor 142)
Description:
Highly selective G protein-coupled receptor for aromatic amino acids specifically L-Tryptophan (L-Trp) and L-Phenylalanine (L-Phe), with L-Trp being the most potent and efficacious agonist. GPR142 agonists triggers the activation of both GNAQ/G(q) and GNAI1/G(i)-coupled signaling pathways. L-Trp stimulates glucose-induced insulin secretion and triggers G(q)-mediated signaling (By similarity). GPR142 appears to have a role as a sensor of aromatic essential amino acids controlling the secretion of both insulin in the pancreas and other gastrointestinal hormones including glucagon but also CCK and incretin in the gastrointestinal-tract, contributing to the control of glucose homeostasis by coordinating pancreatic and gut hormone secretion (By similarity).
Synonyms: GPRG1B; PGR2
Tractability: Small molecule: a high-quality ligand is known; it belongs to a druggable protein family. Antibody: its Gene Ontology location is reachable by antibodies, with high confidence; UniProt places it where antibodies can reach, with medium confidence; UniProt predicts a signal peptide or a membrane-spanning region. PROTAC: a small molecule that binds it is known.
Target class: Family A G protein-coupled receptor; Membrane receptor
Chemical probes: BI-1046 (high quality)
Gene: Protein-coding gene on chromosome 17 (74,367,458 to 74,372,600, forward strand). Ensembl gene ENSG00000257008.
Subcellular location: Cell membrane
Subcellular location (Human Protein Atlas): Cytosol; Plasma membrane; Cell Junctions
Gene Ontology:
Molecular function: G protein-coupled receptor activity
Biological process: glucose homeostasis; phospholipase C-activating G protein-coupled receptor signaling pathway; G protein-coupled receptor signaling pathway
Cellular component: membrane; plasma membrane
Genetic constraint (gnomAD): Loss-of-function variants: 7 observed, 8.05 expected, observed/expected ratio (o/e) 0.87, 90% interval 0.49 to 1.6. That is too few expected variants to judge how well the gene tolerates losing a copy. Missense variants: 469 observed, 499.38 expected, observed/expected ratio (o/e) 0.94, 90% interval 0.87 to 1.01. Synonymous variants: 193 observed, 211.1 expected, observed/expected ratio (o/e) 0.91, 90% interval 0.81 to 1.03.
Homologues: Orthologues: chimpanzee GPR142 (93% identical), macaque GPR142 (88% identical), pig GPR142 (77% identical), dog GPR142 (76% identical), guinea pig GPR142 (75% identical), rat Gpr142 (70% identical), mouse Gpr142 (68% identical), rabbit GPR142 (67% identical), tropical clawed frog gpr142 (46% identical), zebrafish gpr142 (45% identical), Drosophila melanogaster FMRFaR (21% identical), Drosophila melanogaster Proc-R (19% identical), and 133 more. Paralogues in human: GPR139 (36% identical).
Diseases named in the same sentence as GPR142 in open-access papers:
GPR142 is named in the same sentence as 9 diseases in open-access papers, as found by Europe PMC text mining. Sharing a sentence is not in itself a finding about the gene and the disease. The quoted sentences say what the papers report.
type 2 diabetes (5 papers, 2016 to 2021). "Aside from this, we should consider the possibility of GPR142 being an indirect mediator in the numerous kinds of cancer, such as pancreatic, endometrial, breast, liver, colorectal, bladder and kidney cancer, that have been positively associated with type 2 diabetes." (PMID 33113952, 2020). "This has motivated the design of synthetic GPR142 agonists, one of this has recently reached phase 1 in clinical trials for Type 2 diabetes treatment." (PMID 33113952, 2020). "Together, our data indicate GPR142 agonism represents an attractive approach for the treatment of type 2 diabetes." (PMID 27104960, 2016). "GPR142 is an islet-enriched G protein-coupled receptor that has been investigated as a novel therapeutic target for the treatment of type 2 diabetes by virtue of its insulin secretagogue activity." (PMID 27104960, 2016). "GPR139 homolog GPR142 shares the activation by L-Trp and L-Phe but is mainly expressed in the pancreas and gut, where it regulates insulin and incretin secretion, respectively, making GPR142 a potential target in type II diabetes." (PMID 34943862, 2021). "We previously published complete biochemical pathway of GPR142 network involved in type 2 diabetes." (PMID 29492402, 2018). "As a novel insulin secretagogue mechanism, it is important to determine whether GPR142 agonists stimulate insulin secretion only in the presence of high ambient glucose, which is essential for a desired safety profile for the treatment of type 2 diabetes." (PMID 27104960, 2016). "In conclusion, GPR142 agonists may represent a novel therapeutic approach that leverages amino acid sensing pathways in both the gastrointestinal tract and pancreatic islets for the treatment of type 2 diabetes." (PMID 27322810, 2016). "In conclusion, these findings demonstrate GPR142 is a Tryptophan receptor critically required for insulin and incretin hormone regulation and suggest GPR142 agonists may be effective therapies that leverage amino acid sensing pathways for the treatment of type 2 diabetes." (PMID 27322810, 2016).
diabetes (4 papers, 2016 to 2021). "In summary, our data indicate GPR142 agonism as a novel therapeutic approach for the treatment diabetes has minimal risk for hypoglycemia." (PMID 27104960, 2016). "Hence, GPR142 can be a potentially advantageous drug target for diabetes therapy and can provide an alternative therapy with reduced risk of hypoglycemia." (PMID 29492402, 2018).
Obesity (3 papers, 2008 to 2018). Accumulation of substantial excess body fat. "In the absence of an exogenous amino acid challenge, metabolic abnormalities of Gpr142-deficient mice are modest, even when subjected to high-fat diet (60 kcal% fat) feeding to induce obesity and metabolic dysfunction." (PMID 27322810, 2016). "We examined GPR142 mRNA expression levels in the stomach and pancreas of diet-induced obesity (DIO) and ob/ob mice to explore if chronic energy balance affects GPR 142 mRNA levels." (PMID 29889885, 2018). "Given the high level of GPR142 expression in so many tissues and its drug accessibility as receptor, this would appear to be an ideal anti-obesity drug target." (PMID 18752667, 2008). "Results from knockdown of a zebrafish G-PCR ortholog previously determined to decrease fat content in C. elegans support that future GPR142 antagonists may be effective non-toxic anti-obesity therapeutics." (PMID 18752667, 2008).
Arthritis (1 paper, 2024). Inflammation of a joint. "GPR139 is present mainly in the central nervous system but GPR142 is highly expressed on immune cells and it was found that its receptor antagonist CLP-3094 alleviated collagen antibody-induced arthritis in mice." (PMID 38612652, 2024).
fusariosis (1 paper, 2017). "Further, human orthologues of 4 genesenriched in neurons, namely tkr-3 (orthologue GPBAR1), ugt-8(orthologue UGT3A2), R05G6.5.1 (orthologue NME5), and srw-85(orthologue GPR142) might act as potential candidates to unravel the link betweenneuronal stress and fusariosis." (PMID 29152379, 2017).
papillary renal cell carcinoma (1 paper, 2020). A rare subtype of renal cell carcinoma, arising from the renal tubular epithelium and showing a papillary growth pattern, which typically manifests with hematuria, flank pain, palpable abdominal mass or nonspecific symptoms, such as fatigue, weight loss or fever. "As far as we know, there is only one study linking one missense mutation in GPR142 gene with type 1 and type 2 papillary renal cell carcinoma, and suggesting therefore that GPR142 might be involved in this type of cancer." (PMID 33113952, 2020).
cancer (2 papers, 2020). A tumor composed of atypical neoplastic, often pleomorphic cells that invade other tissues. "All hits with < −1.0 vector score and <0.0 volume score were rejected.The Compound1, Compound2, and Compound3 were obtained after screening from the 3D database of GPR142, having the same pharmacophoric features that inhibit cancer." (PMID 33679382, 2020). "This suggests the possible role of novel GPR139 and GPR142 as the substances for initiating a physiological response to handle the condition incurred as a result of cancer." (PMID 33679382, 2020).
tumor (2 papers, 2020 to 2023). "The current work initially analyzes GPR139 and GPR142 for its genomic alteration via tumor samples." (PMID 33679382, 2020). "In-depth analysis of the DEGs that exhibited significant changes in K562 cells treated with WIP2W showed an elevation of tumor suppressor genes, including OSCP1, and genes related to cell apoptosis such as FXYD6, NPTX1, and GPR142." (PMID 37765274, 2023).
GPR142 also shares sentences with these, for which no sentence is quoted: Hypoglycemia (2 papers).